C3AR1 (complement C3a receptor 1)
Diseases named in the same sentence as C3AR1 in open-access papers (continued):
Sharing a sentence is not in itself a finding about the gene and the disease.
cancer (continued). "Studies indicate that some oncogenic proteins regulate the infiltration of immune cells into tumors; however, our correlation analysis revealed that the expression levels of C3, C3AR1, and C5AR1 were strongly associated with the infiltration of immune cells into tumors across the TCGA cancer types." (PMID 34439277, 2021). "C3AR1 shows a very strong correlation (r > 0.7) with the infiltration of dendritic cells in 23 types of TCGA cancers, and a strong correlation (r = 0.5~<0.7) with the infiltration of dendritic cells in five cancer types (SKCM-Metastasis, UCEC, OV, TGCT, and BLCA)." (PMID 34439277, 2021). "Our results suggest the involvement of C3 and C3AR1 in the resistance of human cancer cell lines to small molecules drugs, while the expression levels of C5AR1 and C3AR1 could predict the response to chemotherapy in breast, ovarian, colorectal, and GBM cancer patients." (PMID 34439277, 2021). "We found that 30 of these genes which included Nckap1l, Ncf1, Pla2g15, Unc93b1, Lrrc33, Rgs10, Gmfg, Rbm25, C3ar1, Ccdc88b, Fam105a, Gng11, Phc1, Rasa4, Dag1, Tyrobp, Tmsb4x, Cfp, Prkd1, Gp49a, Trem2, C1qc, Lyz2, Igfbp7, Rab30, Cxcl16, Egfl7, Ube2r2, Pltp, and Cfb, showed a relation with cancer." (PMID 32812032, 2020). "We used the differential gene expression module of TIMER to evaluate the differential expression of C3, C5, C3AR1, and C5AR1 between human cancer and normal tissues across the TCGA database." (PMID 34439277, 2021). "More biological evidence is required to further understand the role of the complement components C3, C5, C3AR1, and C5AR1 in cancer progression." (PMID 34439277, 2021). "In conclusion, the complement components C3, C5, C3AR1, and C5AR1 serve as attractive targets for strategizing cancer immunotherapy and response follow-up." (PMID 34439277, 2021). "Collectively, C3, C5, C3AR1, and C5AR1 demonstrated context-dependent expression in and a prognostic impact on various cancer types." (PMID 34439277, 2021). "We assessed the correlation of C3, C5, C3AR1, and C5AR1 expression with infiltrations of six types of immune cells across the TCGA cancer types." (PMID 34439277, 2021). "The complement components C3, C5, C3AR1, and C5AR1 serve as attractive targets for strategizing cancer immunotherapy and response follow-up." (PMID 34439277, 2021). "Finally, we extracted the top 20 in-degree and top 20 out-degree genes as the hub nodes of each cancer and identified six co-owned immune feature genes (CD48, GPR65, C3AR1, CD2, CD3E and ARHGAP9) in these cancers." (PMID 35069897, 2022). "Collectively, our study demonstrates that the complement component proteins C3, C5, C3AR1, and C5AR1 are candidate biomarkers for cancer diagnosis, prognosis, and therapy outcomes, and thus serve as attractive targets for strategizing cancer immunotherapy and the response follow-up." (PMID 34439277, 2021).
infection (28 papers, 2012 to 2026). The state of being infected such as from the introduction of a foreign agent such as serum, vaccine, antigenic substance or organism. "We, therefore, used our CEACAM1-humanized mouse model in combination with deficiencies in C3 (C3−/-), C5 (C5−/-), C3aR1 (C3ar1-/-) C5aR1 (C5ar1−/-) or C5aR2 (C5ar2−/-) to monitor Nme nasal colonization following intranasal infection with 105 CFU." (PMID 31274379, 2019). "There was also an increased transcription of the gene encoding Complement component 3a receptor 1 (C3AR1), which is the 3a peptide receptor, one of the proteins of the complement cascade that opsonizes pathogens, and induces a series of inflammatory responses that help fight infection." (PMID 25259715, 2014). "We found two components of this system (C1R and C3AR1) as well as an inhibitor to this cascade (SERPIN1) to all be upregulated during infection in addition to the equine miR-6852-5p, which is predicted to target C1R ligand." (PMID 33430330, 2021). "Genes related to resistance to infection, cytotoxicity, cell death, and G protein-coupled receptor signaling such as c3ar1, hif1α, il22, and ifnγ were highly expressed in mice colonized with P. aeruginosa PA14 WT." (PMID 30867416, 2019). "Furthermore, the heatmap of the DEG list highlighted the significant upregulation of multiple genes related to the complement system on D1 and D7 post-infection, including complement C3, C3ar1, Itgax, Itgb2, and C1ra." (PMID 40294039, 2025). "Additionally, the C1qb and C3ar1 genes were significantly upregulated in all infection groups except in Omicron-infected lungs at 3 dpi." (PMID 40416961, 2025). "Thus, our aim was to assess the influence of TLR2 and the anaphylatoxin receptors, C3aR1 and C5aR1, during infection with scrapie strain 22L." (PMID 30596651, 2018). "Furthermore, infection induced the expression of C3aR (C3ar1) and C5aR1 (C5ar1)." (PMID 33613523, 2020). "Sixteen cattle complement genes, including complement C2, complement factor B (CFB), complement C1r (C1R), C1R-like, C3aR1, complement factor properdin (CFP) and complement factor I (CFI) were upregulated two- to 10.6-fold in response to the infection." (PMID 41398915, 2025).
neurodegenerative disease (11 papers, 2021 to 2026). A disorder of the central nervous system characterized by gradual and progressive loss of neural tissue and neurologic function. "Endothelial C3AR1 regulates vascular inflammation in aging or neurodegenerative diseases." (PMID 39108264, 2024). "Endothelial C3AR1 regulates vascular inflammatory response in aging or neurodegenerative diseases." (PMID 33748161, 2021).
kidney disease (9 papers, 2018 to 2026). "C3AR1: GWASs have implicated the C3AR1 locus in kidney disease risk and renal function." (PMID 41322097, 2025).
C3AR1 also shares sentences with these, for which no sentence is quoted: Stroke (21 papers); Cerebral ischemia (9); Insulin resistance (8); glioblastoma (7); viral infection (7); depression (6); ischemic stroke (6); Arthritis (5); lung carcinoma (5); brain injury (4); colon cancer (4); glomerulosclerosis (4); lupus nephritis (4); myocardial infarction (4); pancreatic cancer (4); preeclampsia (4); sarcoma (4); colitis (3); glomerular disease (3); IgA nephropathy (3); inflammation (3); membranous nephropathy (3); renal failure (3); renal fibrosis (3); acne (2); airway hyperresponsiveness (2); allergic asthma (2); Allergy (2); autoimmune disease (2); Autoimmunity (2).
A further 124 diseases each share a sentence with C3AR1 in 2 papers or fewer.